BRCA1 (BRCA1 DNA repair associated)
Diseases named in the same sentence as BRCA1 in open-access papers (continued):
Sharing a sentence is not in itself a finding about the gene and the disease.
pancreatic cancer (continued). "Hereditary diffuse gastric cancer (caused by for example CDH1) and hereditary pancreatic cancer (caused by for example BRCA1/2) have been defined more recently based on identification of gene defects in high-risk phenotype families." (PMID 37165697, 2023). "Tumours of pancreatic cancer patients harbouring BRCA1/2 heterozygous germline variants show a loss of heterozygosity of the functional wildtype allele and thus are sensitive to platinum agents." (PMID 37951914, 2023). "Because of the scarcity of non-BRCA mutations in FPC, the clinical benefit of PARPi and other therapeutic strategies have only been focused on pancreatic cancer with BRCA1/2 mutations." (PMID 37735513, 2023). "BRCA1/2 mutations have been identified in familial pancreatic cancers, with the majority being germline BRCA2 gene mutations, which occur in approximately 5–17% of patients with familial pancreatic cancer." (PMID 37035242, 2023). "Rucaparib was evaluated in a phase II trial as a maintenance regimen for advanced pancreatic cancer (including both metastatic and locally advanced cases) in patients harboring BRCA1, BRCA2 or PALB2 germline or somatic mutations." (PMID 37366887, 2023). "Pathogenic mutations in BRCA2 occur in 2% of patients with pancreatic cancer, and mutations in BRCA1 in 1% of patients." (PMID 36902416, 2023). "For example, a maintenance regimen with PARP inhibitor olaparib improves PFS in patients with germline BRCA1/2-mutated pancreas carcinoma." (PMID 35834132, 2023). "In the case of pancreatic cancers, germline mutations occur in about 10–20% of patients, with mutations in BRCA1 and BRCA2 being the most common." (PMID 35626055, 2022). "This is a rare outcome, since the link between BC and pancreatic cancer has been reported for advanced-stage BC and related through rare BRCA1 and BRCA2 mutations." (PMID 36612726, 2022). "Promising safety and efficacy profiles have also been shown in rucaparib-based regimens for BRCA1/2 variant pancreatic cancer." (PMID 35685436, 2022). "In a retrospective study of 71 BRCA1/2 associated pancreatic cancer, unresectable pancreatic cancer patients treated with platinum agents had significantly longer OS than those treated with non-platinum agents (22 vs. 9 months; p = 0.039)." (PMID 35163129, 2022). "In classically BRCA-associated tumors, such as breast, ovarian, prostate, and pancreas cancers, BRCA1/2 behave as drivers, exhibiting zygosity-dependence, selection for biallelic inactivation, and potential benefit from PARP inhibition." (PMID 36418296, 2022). "The results show no confirmed response, suggesting that development of other therapeutics are needed for the pancreatic cancer patients with BRCA1/2 or PALB2 mutations." (PMID 35328658, 2022). "Pathogenic BRCA2 and BRCA1 mutations are found in approximately 2%, and ≤1% of pancreatic cancers, respectively." (PMID 35720978, 2022). "Loss of heterozygosity of hereditary pancreatic cancer susceptibility genes such as BRCA1/2 plays a key role in carcinogenesis and sensitivity to PARP inhibitors." (PMID 35163129, 2022). "The selected pancreatic cancer patients with BRCA1/2 and PALB2 mutations and HRD are included in this study." (PMID 35328658, 2022). "This phase 2 trial evaluates the efficacy of veliparib (ABT-888, PARPi) in 16 patients with previously treated BRCA1/2- or PALB2-mutated pancreatic cancer." (PMID 35328658, 2022). "Another phase 2, open-label study assessed the efficacy and safety of olaparib in 23 advanced pancreatic cancer patients with confirmed genetic BRCA1 or BRCA2 mutations (NCT01078662)." (PMID 35228986, 2022). "This phase 2 trial evaluates the efficacy of olaparib in 299 patients with advanced breast, ovarian, prostate, and pancreatic cancers harboring BRCA1 and/or BRCA2 mutations." (PMID 35328658, 2022). "Accordingly, RoIQ is a valuable target for preventing or treating cancers such as breast cancer, ovarian cancer, prostate cancer, and pancreatic tumor retaining BRCA1 deficiency." (PMID 36186578, 2022).
pancreatic cancer (continued). "A phase II, single-arm study evaluating the role of rucaparib as the maintenance therapy for advanced pancreatic cancer with the germline or somatic mutations in BRCA1, BRCA2, or PALB2 enrolled 46 patients, 42 of whom were eligible for the evaluation." (PMID 36556296, 2022). "Germline mutations in BRCA1/2 and other DNA repair genes are associated with an increased risk of breast, ovarian, prostate and/or pancreatic cancer." (PMID 35494038, 2022). "PARP inhibitors are approved in malignancies associated with germline BRCA1/2 PV such as breast, ovarian, prostate, and pancreatic cancer." (PMID 36577523, 2022). "The lifetime risk of pancreatic cancer is about 1% for BRCA1 mutant carriers and 4.9% for BRCA2 mutant carriers." (PMID 35163129, 2022). "The first patient who received olaparib maintenance treatment was a 54-year-old man with metastatic pancreatic cancer and a germline BRCA1 mutation (c.3412 + 1G > T)." (PMID 36463295, 2022). "Recommendations from the two groups differ with respect to patients with pathogenic BRCA1 variants, hereditary pancreatic cancer, and family history." (PMID 35163129, 2022). "BRCA1 is seen in up to 2.4% of pancreatic cancer patients, with up to a three-fold higher risk of developing pancreatic cancer." (PMID 35228986, 2022). "Pathogenic variants in BRCA1 were significantly associated with increased risk of 5 cancer types: ovarian, female breast, biliary tract, gastric, and pancreatic cancers." (PMID 35420638, 2022). "Olaparib, a PARPi, is being evaluated in adjuvant setting in a randomized phase II trial for resectable pancreatic cancer with germline BRCA1/2 or PALB2 mutation after perioperative chemotherapy (NCT04858334)." (PMID 35948602, 2022). "In a study of whole genome sequencing data of pancreatic cancer patients with pathogenic variants of BRCA1/2 or PALB2, signature 3 mutations, and genomic instability were correlated with platinum response." (PMID 35163129, 2022). "Germline BRCA1/2 mutations are common in Chinese patients with hereditary breast, ovarian, prostate and pancreatic cancers." (PMID 36439508, 2022). "BRCA2 was also reported as the most frequent gene in the germline in pancreatic cancer patients, with a prevalence rate of 1.9%; the frequency of BRCA1 variants was 0.5%." (PMID 36439508, 2022). "Similar to BRCA2, BRCA1 mutations also increase the risk of pancreatic cancer (relative risk, 2.26; 95% CI: 1.26–4.06)." (PMID 35884779, 2022). "Tier I or II mutations related to hereditary cancer syndrome in pancreatic cancer were identified in BRCA1 (n = 2, 2.3%), BRCA2 (n = 2, 2.3%), PRSS1 (n = 1, 1.1%), MSH6 (n = 2, 2.3%), PMS2 (n = 1, 1.1%), and APC (n = 1, 1.1%)." (PMID 36463295, 2022). "Cisplatin is a crucial agent for treatment of pancreatic cancer patients with BRCA1/2 or PALB2 mutation." (PMID 35662734, 2022). "Over the last decade, the genetics associated with pancreatic cancer has been intricately assessed Some well-known cancer gene germline mutations have been identified in patients with pancreatic cancer, including BRCA1/2, PALB2, STK11, PRSS1, SPINK1 and ATM." (PMID 35813042, 2022). "The relative risk for pancreatic cancer in BRCA1 and BRCA2 mutant carriers is 2.3 and 3.5–10, respectively." (PMID 35163129, 2022). "Mutations in the BRCA1 tumor suppressor gene, such as 5382insC (BRCA1insC), give carriers an increased risk for breast, ovarian, prostate, and pancreatic cancers." (PMID 36346676, 2022). "A phase II study evaluated maintenance rucaparib in patients with platinum-responsive pancreatic cancer and a pathogenic germline and somatic variant in BRCA1, BRCA2, or PALB2." (PMID 35163129, 2022). "BRCA1 also increases the relative risk (RR) for pancreatic cancer by 2 to 4-fold, where BRCA2 increases RR by 3 to 8-fold." (PMID 35813042, 2022).
pancreatic cancer (continued). "The first is termed hereditary pancreatic cancer, which occurs in individuals with a known hereditary cancer syndrome caused by germline single gene mutations (e.g., BRCA1/2, CDKN2A)." (PMID 35761384, 2022). "Most familial pancreatic cancer (FPC) is attributable to HBOC syndrome that results from germline mutations in BRCA1/2 genes and other genes such as ATM, BRIP1, CHEK2, RAD50, and RAD51C." (PMID 35205366, 2022). "It has been reported that 25% of the patients with BRCA1/2 gene germline mutations are at risk of developing pancreatic cancer, and the lifetime risk of developing pancreatic cancer in patients with BRCA1/2 gene germline mutations is estimated to be 3–8%." (PMID 33562094, 2021). "In a clinical trial (NCT02042378), rucaparib proved to be safe and clinically relevant in advanced pancreatic cancer patients with BRCA1/2 mutations." (PMID 33804613, 2021). "BRCA1 mutations have also been involved in the occurrence of other cancers, including prostate and pancreatic cancer." (PMID 35096615, 2021). "BRCA1 or BRCA2 germline mutations reportedly increase the relative risk of pancreatic cancer by 2.26-fold (1.26−4.06) and 3.51-fold (1.87−6.58), respectively." (PMID 33562094, 2021). "In a large cohort comprising 2,818 sporadic pancreatic cancers, our group identified gene mutations in BRCA1, BRCA2, or PALB2 in 1.3%, 3.1%, and 0.6%, respectively." (PMID 34707985, 2021). "The 3.2019 version of NCCN guidelines (National Comprehensive Cancer Network (NCCN), 2019) for pancreatic cancer recommends that all patients with pancreatic cancer should be sequenced to determine their BRCA1/2 mutation status." (PMID 33959007, 2021). "An increased prevalence of pancreatic cancer was found in families where c.9976A>T occurred together with other pathogenic BRCA1 variants." (PMID 33672545, 2021). "Patient with BRCA1 P/LP variants had Gleason score 6 with family history of gastric, thyroid, prostate and pancreatic cancers." (PMID 33649982, 2021). "Recent studies suggested that germline BRCA mutations are also correlated with an increased risk of developing pancreatic cancer, and up to 8% of patients with BRCA1/2 mutated genes." (PMID 34497764, 2021). "PARP inhibitors show significant clinical efficacy in tumor types that are often associated with BRCA1/2 mutations, such as breast, ovarian, prostate, and pancreatic cancer." (PMID 34145376, 2021). "F79 treatment showed a synergistic effect with imatinib in BRCA1/2-deficient breast, ovarian, and pancreatic cancer." (PMID 33922657, 2021). "An increased frequency of pancreatic cancer was found in families where c.9976A>T occurred together with other pathogenic BRCA1 variants." (PMID 33672545, 2021). "In another ongoing phase II clinical trial (NCT03140670), rucaparib is being tested on pancreatic cancer patients with a locally advanced or metastatic disease possessing a germline or somatic deletion in BRCA1/2 or PALB2 mutations." (PMID 33804613, 2021). "For example, BRCA1 mutations in breast and pancreatic cancer are associated with increased density of tumor-associated macrophages (TAMs) and T cells, as compared to wildtype tumors and BRCA2 mutant tumors." (PMID 34572943, 2021). "The association between pancreatic cancer and BRCA1 is well established, with up to 10% of familial pancreatic cancer being attributable to either a BRCA1 or BRCA2 variant." (PMID 35155181, 2021). "Given we find mutated BRCA1/BRCA2 genes in a significant proportion of patients with familial pancreatic cancer, the utility of these PARPi have been explored in PDAC trials." (PMID 34771675, 2021). "In a phase II trials of olaparib and rucaparib, pancreatic cancer patients with BRCA1/BRCA2 mutations showed response rates of 22% and 16%, respectively." (PMID 34771675, 2021).
pancreatic cancer (continued). "In the National Clinical Cancer Network (NCCN) guidelines, revised in 2020, familial pancreatic cancer (FPC) was included in the HBOC syndrome because FPC harbors BRCA1/2 germline variants to some extent." (PMID 33413558, 2021). "Stage 3 or 4 pancreatic cancer survival increased from 9 to 22 months for those with a BRCA1/2 mutation (P = 0.039) if a platinum-based chemotherapy was introduced into their care." (PMID 32793315, 2020). "Although over 80% of familial pancreatic cancer cases harbor mutations in BRCA1/2 and ATM, germline deletion and mutations of BAP1 have also been observed." (PMID 32541668, 2020). "BRCA1/2 genes, originally known for their association with breast (BC) and ovarian (OvC) cancers, has also been implicated in PC and pancreatic cancer (PaC)." (PMID 33351846, 2020). "Pancreas cancer patients with a germline pathogenic variant in BRCA1/2 or other DDR gene were identified retrospectively through review of medical records (medical genetics/oncology) and genetic testing results at our institution." (PMID 32793315, 2020). "As shown in both ovarian and breast cancer, the POLO trial demonstrated the potential for PARP inhibition in pancreatic cancer, likely setting a new standard of care in patients presenting pancreatic cancer with germline BRCA1 or BRCA2 mutation." (PMID 32635552, 2020). "Mutations in the Brca1 gene were found in urothelial tumors, pancreatic cancer, and prostate malignancies." (PMID 32053991, 2020). "Hereditary breast, ovarian, and pancreatic cancers are associated with the presence of germline pathogenic (P) or likely pathogenic (LP) variants in the BRCA1 and BRCA2 genes." (PMID 32957588, 2020). "Median all stage overall pancreatic cancer survival has been reported as 14 months for those with a pathogenic BRCA1/2 variant." (PMID 32793315, 2020). "For some pancreatic cancers with actionable mutations, such as germline BRCA1/2 mutations, NTRK fusion mutation, and MSI-H, molecular-targeted therapy and immunotherapy are being introduced." (PMID 31997007, 2020). "The POLO trial provided a milestone in targeted therapy of PDAC albeit tailored to a minimal subgroup of around 3–6% of germline BRCA1/2-mutated patients with pancreatic cancer." (PMID 32948057, 2020). "Retrospective studies suggest a survival benefit when platinum-based chemotherapy is administered to patients with pancreatic cancer harbouring a germline mutation in BRCA1, BRCA2 or PALB2 (mut-positive PDAC)." (PMID 31787751, 2020). "In this study, 3315 patients with pancreatic cancer were screened for germline BRCA1/2 mutations, and 247 (7.5%) were found to have BRCA1/2 mutations." (PMID 31997007, 2020). "BRCA1 mutation carriers also have increased risk of other cancers such as pancreatic cancer and prostate cancer." (PMID 32257107, 2020). "Although GEMOX treatment is limited to pancreatic cancers with BRCA1/2 or PABL2 mutations according to the NCCN, it resulted in similar PFS and OS as the other two regimens in unselected Chinese patients." (PMID 33704188, 2020). "In summary, a strong association between pancreatic cancer and BRCA1 and BRCA2 mutations is documented." (PMID 33198203, 2020). "Olaparib (Lynparza) is a first-in-class PARP inhibitor approved for patients with advanced ovarian, breast and pancreatic cancer, particularly those with BRCA1/2 deficiencies." (PMID 32444694, 2020). "We analyzed a homogenous set of BC patients excluding patients with breast and ovarian/pancreatic cancer duplicity and patients carrying mutations in non-BRCA1/BRCA2 BC-susceptibility genes." (PMID 31141992, 2019).
pancreatic cancer (continued). "An estimated 5~10% of pancreatic cancer is familial, with breast cancer susceptibility genes 1/2 (BRCA1/2) and partner and localizer of BRCA2 (PALB2) among established pancreatic susceptibility genes." (PMID 31877165, 2019). "In particular, the National Comprehensive Cancer Network Guideline states that CDDP-based regimens are preferential in the treatment of patients with pancreatic cancer and known BRCA1/2 mutations." (PMID 31450627, 2019). "In case of BRCA1 mutation carriers the relative risk for pancreatic cancer is 3.1 and 6.6 in relatives of BRCA2 mutations carriers." (PMID 29777302, 2018). "The CAPS guidelines do not recommend any surveillance for those with a family history of pancreatic cancer and a pathogenic BRCA1 mutation." (PMID 30186770, 2018). "In patients at risk, including individuals of Ashkenazi Jewish descent or those with a strong family history of pancreas cancer, the prevalence of BRCA1 and BRCA2 germline mutations has been reported in up to 19%." (PMID 29891787, 2018). "In this study, more individuals with a family history of pancreatic cancer had a pathogenic BRCA2 variant, but more of those with a personal history of pancreatic cancer had a BRCA1 variant." (PMID 30186770, 2018). "Of the less common cancers, we observed 1 pancreatic cancer that was interestingly identified in a BRCA1 mutation carrier." (PMID 29433453, 2018). "Somatic mutations and germline genetic variants on BRCA1/2 have been found associated with the tumorigenesis of pancreatic cancer." (PMID 28415599, 2017). "In this present study, we found a tag missense variant (c.4837A>G [p.Ser1613Gly]) on BRCA1 significantly associated with poor prognosis of pancreatic cancer patients in a Chinese population." (PMID 28415599, 2017). "Our work highlighted the important prognostic and predictive value of BRCA1 germline variants, which had been mostly regarded as a risk biomarker of pancreatic cancer though." (PMID 28415599, 2017). "Germline mutations in BRCA1/2 define a molecular subgroup of pancreatic cancers which in some populations has a prevalence as high as 17%." (PMID 28978184, 2017). "We found rs1799966 on BRCA1 was associated with poor prognosis of pancreatic cancer patients with hazard ratio being 1.23 (95% CI: 1.09–1.40, P = 0.0010)." (PMID 28415599, 2017). "In this study, we interrogate the correlation between germline missense variants on BRCA1/2 and pancreatic cancer patients’ overall survival." (PMID 28415599, 2017). "In conclusion, we identified a missense variant rs1799966 on BRCA1 associated with a worse overall survival of pancreatic cancer patients, especially in patients with locally advanced stage." (PMID 28415599, 2017). "In this study, we genotyped three tag missense variants on BRCA1/2 in 603 sporadic pancreatic cancer patients in a Chinese population." (PMID 28415599, 2017). "As a result, we observed that rs1799966 (BRCA1) was significantly associated with pancreatic cancer patients’ overall survival with HR being 1.24 under an additive model (95% CI: 1.09–1.40, P = 0.0010)." (PMID 28415599, 2017). "In the present study, we investigated the impact of germline missense variants on BRCA1/2 and overall survival (OS) of pancreatic cancer patients." (PMID 28415599, 2017). "The study included 178 CDKN2A mutation carriers, 214 individuals with familial pancreatic cancer, and 19 BRCA1/2 or PALB2 mutation carriers." (PMID 29069866, 2017).